HDAC5 (histone deacetylase 5)
Diseases named in the same sentence as HDAC5 in open-access papers (continued):
Sharing a sentence is not in itself a finding about the gene and the disease.
cancer (60 papers, 2006 to 2025). A tumor composed of atypical neoplastic, often pleomorphic cells that invade other tissues. "Application of the FCVPPv2 on a CRC-affected family identified a novel missense variant in the APCDD1 gene and a 5′UTR variant in the HDAC5 gene as potentially cancer predisposing." (PMID 33673279, 2021). "The location of the variant in a CpG island and multiple TFBSs as well as the high PHRED-like CADD score of 21.9 supported the potential functional role of the identified HDAC5 variant in cancer predisposition, leading to its final prioritization." (PMID 33673279, 2021). "HDAC5 can cause significant modifications in heterochromatin structure that trigger cancer cells to undergo apoptosis." (PMID 26993777, 2016). "In addition, there is no universal underlying mechanism of the action of fentanyl on cancer cells, and via either opioid receptor-dependent or -independent mechanisms such as inhibition of Ets-1 and HDAC5, and activation of wnt/β-catenin." (PMID 35999506, 2022). "Therefore, the short-listed 5′UTR variant of the HDAC5 gene (17_42200942_T_G) was considered as a promising cancer-predisposing candidate." (PMID 33673279, 2021). "Thus, serum HDAC5 has clinical utility as a diagnostic biomarker for cancer." (PMID 34178647, 2021). "Further, clinical TNBC tissue microarray staining showed that HDAC5 localized to normal breast nuclei but was downregulated in cancer tissues." (PMID 40963916, 2025). "HDAC5 is overexpressed in various cancers, where its aberrant regulation contributes to malignant phenotypes such as increased cell proliferation, evasion of apoptosis, enhanced invasion, metastasis, and drug resistance." (PMID 40290805, 2025). "For instance, miR-148a-3p can suppress histone deacetylase 5 and enhance cancer cell invasion and migration." (PMID 40433390, 2025). "This HDAC5-driven resistance mechanism uses paracrine actions to attract immune cells supporting cancer cell survival." (PMID 38668053, 2024). "In a variety of normal and cancer cells, HDAC5 levels are regulated by multiple miRNAs including miR-125a-5p, miR-589-5p, miR-2861, miR-9, miR-124, and miR-217." (PMID 38369747, 2024). "Apart from HDAC5, the other five HDACs displayed higher staining and more positive regions in cancer tissues, according to immunohistochemistry results from 3 sets of LIHC tissues and corresponding normal paracancerous tissues." (PMID 39512688, 2024). "There is growing evidence that abnormal expression of HDAC5 plays a role in cancer cell proliferation, metastasis, and invasion, thus contributing to the development and progression of various human tumors (e.g., lung, colon, breast)." (PMID 36910848, 2023). "This suggests that cancer itself can upregulate HDAC5 for hypersecretion of exosomes to regulate the intra-tumoral microenvironment." (PMID 38102691, 2023). "The functions of HDAC5 in tumorigenesis have been investigated in a variety of cancers, and HDAC5 was also shown to promote cell proliferation, invasion and metastasis in cancer." (PMID 36819033, 2023). "Noticeably, our study is the first report the role of HDAC5 in the regulation of p16INK4a expression in GC cells, thus providing a novel HDAC5-mediated pathway in cancer, in addition to the TAp63/maspin, HIPK2/HIF1α, and p65/NF-κB pathways." (PMID 37415735, 2023). "LMK235, an inhibitor of HDAC4 and HDAC5, has been investigated for its antitumor effect on other cancers." (PMID 36139696, 2022). "HDAC5 interacts with the immune system—including immune cells and inflammatory cytokines—in cancer occurrence or progression." (PMID 34178647, 2021).
cancer (continued). "The findings to date indicate that HDAC5 is epigenetically modified and regulated at the transcriptional level, providing new avenues for HDAC5-based cancer therapy." (PMID 34178647, 2021). "TSA was illustrated to inhibit HDAC5 to block malignant behavior of cancer cells, including chemoresistance, proliferation and invasion." (PMID 34178647, 2021). "Circulating HDAC5 is a potential marker for cancer diagnosis, given that it is detected at different levels in the peripheral blood of cancer patients as compared to healthy subjects or patients with nonrecurrent disease." (PMID 34178647, 2021). "In this review, we summarize recent findings on the biological activities of HDAC5 in several common cancers and cancer-related processes." (PMID 34178647, 2021). "Accumulating evidence indicates that HDAC5 can serve as a biomarker for tumorigenesis in a variety of cancer types." (PMID 34178647, 2021). "HDAC5 expression is correlated with clinicopathologic features of cancer patients, highlighting its clinical value." (PMID 34178647, 2021). "In light of recent findings regarding the role of epigenetic reprogramming in tumorigenesis, in this review, we provide an overview of the expression, biological functions, regulatory mechanisms, and clinical significance of HDAC5 in cancer." (PMID 34178647, 2021). "Collectively, these findings highlight the clinical significance and utility of HDAC5 in targeted cancer therapy." (PMID 34178647, 2021). "Aberrant expression of HDAC5 has been observed in multiple cancer types, and its functions in cell proliferation and invasion, the immune response, and maintenance of stemness have been widely studied." (PMID 34178647, 2021). "In HCC, class I HDAC1 and HDAC2 were mainly reported to be associated with poor prognosis, but inhibition of class II HDAC, HDAC4 and HDAC5 has also been reported to have significant anti-cancer effects." (PMID 32977608, 2020). "Five HDAC genes (HDAC2, HDAC4, HDAC5, HDAC10, and SIRT3) showed copy number loss in at least two cancer types." (PMID 30760718, 2019). "Several previous studies have provided data on the pathophysiologic role of HDAC5 in cancer: HDAC5 was found to regulate heterochromatin assembly and cell proliferation in cancer cells and to enhance the effect of chemotherapy." (PMID 30321986, 2018). "AR-42 inhibited cancer cell proliferation through the induction of cell apoptosis primarily by targeting HDAC5." (PMID 26993777, 2016). "In contrast, LMK-235, a novel class IIa HDACi with a preference for HDAC4 and HDAC5, displayed potent cytotoxic effects in human cancer cell lines." (PMID 27177225, 2016). "•HDAC5 knockdown increased the osimertinib-sensitivity of EGFR-mutant cancer cells." (PMID 40290805, 2025). "Furthermore, we downloaded paired data from the TCGA database for TNBC tissues and found that HDAC5 expression was lower in cancer tissues compared to adjacent normal tissues, providing big data support for the upregulation of HDAC5 by SSD." (PMID 40963916, 2025). "The association of upregulation of HDAC5 with sensitivity to multiple kinases and of HDAC1 with dasatinib sensitivity is unexpected, based on frequently reported clinical benefits of inhibition of their products in cancer treatment." (PMID 38369747, 2024). "Furthermore, there is evidence that HDAC5 frequently shows low expression levels in human malignant tumors." (PMID 36910848, 2023). "Clarifying the mechanisms that enact HDAC4 and HDAC5 localization induced by μsPEF exposure of mammalian cells has significant translational implications due to the pervasive roles of class IIa HDAC’s in cancer." (PMID 36466344, 2022). "Aberrant HDAC5 expression has been observed in multiple cancer types." (PMID 35359455, 2022). "In addition, HDAC5 also functioned as a downstream target gene of various upstream factors and participated in the regulatory pathways during cancer progression." (PMID 34178647, 2021).
cancer (continued). "The contribution of HDAC5 to cancer cell proliferation has been investigated in many studies." (PMID 34178647, 2021). "As such, clarifying the role and mechanisms of HDAC5 in cellular differentiation may provide a basis for new therapeutic strategies in cancer." (PMID 34178647, 2021). "The functions of HDAC5 in tumorigenesis have been investigated in a variety of cancers." (PMID 34178647, 2021). "Some studies support our results, showing that increased expression of autotaxin in PCa cell lines is mediated by the downregulation of HDAC7 and HDAC3; additionally, HDAC5 is downregulated in human cancer, namely PCa, and decreased expression of HDAC4 increases the growth of PCa cells." (PMID 34833128, 2021). "Recent studies have demonstrated the involvement of HDAC5 in cancer cell apoptosis." (PMID 34178647, 2021). "Class I histone deacetylases (HDACs) generally promote cell proliferation and tumorigenesis, whereas class IIA HDACs like HDAC4 and HDAC5 may promote or impede cancer development in a tissue-dependent manner." (PMID 31052182, 2019). "While HDAC5 has previously been identified as a factor in fibrosis and cancer progression, this is, to our knowledge, the first report demonstrating that HDAC5 on its own may induce EMT in certain circumstances." (PMID 31052182, 2019). "Earlier studies found that HDAC5 inhibition induces apoptosis in cancer cells." (PMID 30321986, 2018). "Over-activation of HDAC5 was found in many different types of cancer." (PMID 30286788, 2018). "The role of HDAC5 in tumorigenesis and cancer progression is controversial." (PMID 27177225, 2016). "In addition, studies in cancer cells have revealed the involvement of the histone deacetylase 5 (HDAC5) in maintaining telomere length." (PMID 25366419, 2015). "Therefore, blocking glucose and glutamine metabolism in HDAC5-knock down cancer cells significantly induced cell death, which provided insight into a combination therapy with HDAC5 inhibitors and various inhibitors of metabolism as a new strategy for cancer treatment." (PMID 34178647, 2021). "LMK235 was originally synthesized to inhibit both HDAC5 and HDAC4, and thus, we cannot exclude the possibility that its anti-cancer effects involve inhibition of endogenous HDAC4 activity." (PMID 40290805, 2025). "Upregulation of miR-125a and miR-125a-5p in cancer cells by HDAC inhibitors and regulation of HDAC5 protein levels by miR-125a-5p was experimentally demonstrated." (PMID 38369747, 2024). "In HDAC5-rich tumors, these macrophages increase TGFβ production, triggering pSMAD3/SMAD4 signaling in cancer cells, and bypassing the need for KRAS." (PMID 38668053, 2024). "In fact, in the mRNA seq data of cancer tissues and paired adjacent tissues of HCC patients, the expression of HDAC5 was significantly increased in cancer tissues." (PMID 38102691, 2023). "Overall, our study identified that CD13 as a regulator in cancer progression and sorafenib resistance by forming CD13/HDAC5 complex and regulating NF‐κB p65 acetylation." (PMID 33377659, 2020). "Our findings call for further analyses of the relation between HDAC5 on the one hand, and EMT and fibrosis, on the other hand, in cancer and other diseases." (PMID 31052182, 2019). "LMK-235, a novel HDAC class IIA HDACi specifically inhibiting HDAC5 (IC50 = 4.22 nM) and HDAC4 (IC50 = 11.9 nM), was found to be cytotoxic in several human cancer cell lines." (PMID 30321986, 2018). "Analysis of RNA-seq data from 34 normal gastric tissues and 415 primary GC revealed significant upregulation of B7-H1; HDAC1–3, 6–8, and 10; and SIRT1, 3, 5, and 6 and downregulation of HDAC5 and SIRT4 in cancer (only data of B7-H1 and HDAC1–3 was presented)." (PMID 30537988, 2018). "We also analyzed the correlation between CSNK2B expression and HDAC family‐related genes in the TIMER2.0 public database of multi‐cancer, and we found that the expression of CSNK2B showed a positive correlation with HDAC1, HADC2, HDAC5, HDAC6, and HDAC8 in LUAD and LUSC." (PMID 40013761, 2025).
cancer (continued). "It is worth noting that, unlike other HDAC classes, Class II HDAC member HDAC5 is typically downregulated or deleted in various human cancers, with a significant correlation to patient prognosis." (PMID 40963916, 2025). "Curiously, although a range of HDAC inhibitors have been designed and synthesized, many of which are being used to treat cancers in the clinics, no HDAC5 activator or agonist has been reported." (PMID 29212224, 2017). "Both HDAC5 and HDAC6 could influence the metastasis of A375 cells by regulating MMP9 and vimentin, both markers for the metastasis ability of cancer cells." (PMID 26747087, 2016). "These bacteria may affect the host by shedding different microbial bioactive molecules, because heat-killed S. maltophilia and supernatants did not cause proliferation and migration and did not upregulate the HDAC5 gene expression of cancer cells in vitro." (PMID 36819033, 2023). "Although both vorinostat and DMC-HA are inert to HDAC4 and HDAC5, it has been reported that class IIa (including HDACs 4, 5, 7, and 9) enzymes are inefficient on histone substrates; class I HDACs, especially HDACs 1–3, and HDAC 6 (class IIb) are considered key targets for cancer treatment." (PMID 34804949, 2021). "Together with the notion that a high level of HDAC4, HDAC5 and HDAC6 expression has an implication in cancer development, the up-regulation of HDAC4, HDAC5 and HDAC6 of fPMSCs showed in this study may imply a potential risk for malignant transformation for this type of cells." (PMID 25671548, 2015). "Class II HDACs, including HDAC5, HDAC6, and HDAC9, have been reported to catalyze the deacetylation of cytoplasmic, non-histone proteins in cancer cells." (PMID 32977608, 2020). "Indeed, palbociclib is not sufficient to activate HDAC5-dependent RB inhibitory activity in HDAC5 KD cells, but concurrent treatment with NEO3724, a dual BET-CBP/p300 inhibitor, restores sensitivity to palbociclib in cancer cells and xenografts." (PMID 39624079, 2024).
infection (11 papers, 2015 to 2025). The state of being infected such as from the introduction of a foreign agent such as serum, vaccine, antigenic substance or organism. "Our data suggest that disrupting the HDAC5—mTORC1 signaling axis could weaken immunity and increase susceptibility to inflammation and infection." (PMID 40832175, 2025). "C6 is highly conserved in orthopoxviruses, and C6 orthologs from VACV, RPXV, CPXV-BR, CMLV, MPXV, and VARV all degrade HDAC5 outwith infection." (PMID 38461415, 2024). "Infection by many of these viruses induces proteasomal degradation of HDAC5, and expression of C6 alone can induce HDAC5 degradation." (PMID 38461415, 2024). "Previously, we showed that HDAC5 is degraded during Vaccinia virus (VACV) infection and is a restriction factor for VACV and herpes simplex virus type 1." (PMID 38461415, 2024). "The rapid downregulation of HDAC5 by VACV early during infection, and downregulation by a distinct large DNA virus, HCMV, suggested a role in antiviral restriction." (PMID 31067474, 2019). "C6 is the only VACV protein needed for HDAC5 degradation because a VACV strain lacking C6 does not degrade HDAC5, and a cell line that expresses C6 inducibly causes degradation outwith infection." (PMID 38461415, 2024). "In this in vivo model, we demonstrated that mice treated with MS-275 were more prone to AIEC infection compared to untreated mice, whereas LMK-235-treated mice were less susceptible to infection compared to control mice confirming the role of class I HDAC and HDAC5 in AIEC intestinal colonization." (PMID 36175163, 2022). "In addition to HDAC5, we found that all IFITs and certain TRIMs were rapidly degraded during infection." (PMID 31067474, 2019). "HDAC5 was rapidly degraded during infection, was one of the proteins most substantially rescued by MG132, and was also downregulated by HCMV, suggesting that this molecule might be particularly important in the life cycle of diverse viruses." (PMID 31067474, 2019). "Previously, HDAC5 was reported to interact with proteins from other viruses, although had not hitherto been identified as a restriction factor, or shown to be downregulated during infection." (PMID 31067474, 2019). "Moreover, at least five transcription factors, such as the oncogene MYB, SMAD family members 6 and 9 (SMAD6 and SMAD9), and histone decetylase 5 (HDAC5), were significantly affected by infection in CHB." (PMID 27197554, 2016). "HDAC3, HDAC4, HDAC5, and HDAC11 restrict infection of some viruses via regulation of IRF3, nuclear factor κB (NF-κB), or type I interferon (IFN) Janus kinase-signal transducers and activators of transcription (JAK-STAT) signaling pathways." (PMID 38461415, 2024). "Infection with three different VACV strains, as well as CPXV-BR, RPXV, CMVL, CPXV-E, and MPXV, all induce HDAC5 degradation." (PMID 38461415, 2024). "Two-thirds of these viral targets, including class II histone deacetylase 5 (HDAC5), are degraded proteolytically during infection." (PMID 31067474, 2019). "HDAC5, KDM2B, EZH1, PRDM2, SETMAR, SMYD4 and USP12 were differentially expressed at all time points post-infection (excluding 2 hpi)." (PMID 30728374, 2019). "The finding that HDAC5 is downregulated by both HCMV and VACV suggested that this molecule might play an important role during infection, such as in antiviral restriction." (PMID 31067474, 2019). "In contrast, infection of L6 myotubes with Ad-PIMT or Ad-PIMT Ser298Asp but not Ad-PIMT Ser298Ala led to a striking increase in HDAC5 expression." (PMID 26468734, 2015). "Immunoblotting showed that endogenous HDAC5 co-precipitated with TAP-C6, but not TAP-N1, during infection." (PMID 38461415, 2024). "The infection with AIEC bacteria did neither induce significant modulations of HDAC1 and HDAC5 expression nor modification of H3 global acetylation in colonic mucosa of Chow-fed mice." (PMID 36175163, 2022).
infection (continued). "Consistent with the data from cultured cells, infection with Ad-PIMT Ser298Asp but not Ad-PIMT Ser298Ala suppressed GLUT4, MEF2A, MEF2D expression while up-regulating PGC1-α, HDAC5 and MEF2C expression in the rat skeletal muscle tissue." (PMID 26468734, 2015). "Overexpression of HDAC5, but not EYFP, reduced plaque size for CPXV-BR and reduced the yield of infectious virus for CPXV-BR, CMLV, CPXV-E, and RPXV 2 days after infection." (PMID 38461415, 2024). "Studying infection in the presence or absence of the proteasomal inhibitor MG132 showed that 69% of downregulated proteins were targeted for proteasomal degradation, including histone deacetylase 5 (HDAC5)." (PMID 31067474, 2019).
cardiovascular diseases (4 papers, 2013 to 2023). "Analyzed genes were associated with cardiovascular diseases and risk factors (TBC1D22A, WNK1), bone mineral density (HDAC5), body weight (PABPC3), glycerophospholipid metabolism (CDS2), Notch signaling (HDAC5), RNA transport and degradation (PABPC3)." (PMID 32344947, 2020).
cardiac diseases (2 papers, 2016 to 2023). "Future research should explore the role of HDAC5 in different models of heart disease to better understand its function and relevance as a therapeutic target." (PMID 37667300, 2023). "Histone deacetylase 5 (HDAC5) is an important protein in neural and cardiac diseases and a potential drug target." (PMID 27177225, 2016).
brain disorder (1 paper, 2020). A disease affecting the brain or part of the brain. "HDAC5 regulates the homeostasis of histone acetylation, which plays a central role in various brain disorders." (PMID 32046281, 2020).
immune diseases (1 paper, 2008). "We identify four nuclear proteins, HDAC5, TFC4, RTF1 and POLDIP3 polymerase as new autoantigens that could be used as markers in the diagnosis of subfamilies in immune diseases, although we cannot determine the role of these proteins in the aetiopathogenic process." (PMID 18625050, 2008).